CD36 (CD36 molecule (CD36 blood group))
Diseases named in the same sentence as CD36 in open-access papers (continued):
Sharing a sentence is not in itself a finding about the gene and the disease.
tumor (continued). "Following intervention with the cholesterol inhibitor MβCD, the expression of cholesterol synthesis-related proteins (CD36, SREBP2 and HMGCR) decreased, while the expression of cholesterol efflux-related proteins (APOA1 and ABCG1) increased, leading to significant inhibition of tumor cell growth." (PMID 41041664, 2025). "The fatty acid translocase gene CD36 and phospholipase A2 (PLA2), which are responsible for the transport of FAs into the cells and the release of arachidonic acid (ARA), among other things, respectively, show higher expression in para-tumor tissue than healthy thyroid." (PMID 39145825, 2025). "CD36, highly expressed in LN-CAFs, may support lipid metabolism-driven tumor survival in metastatic lymph nodes, whereas COL11A1, elevated in Lung-CAFs, likely enhances ECM remodeling at the primary tumor site." (PMID 40940956, 2025). "Moreover, we identified novel substrates like LGALS3BP, ITGB8, CD36, and ECE1, which may contribute to malignant tumor progression." (PMID 39937175, 2025). "Moreover, tumor-derived cytokines, such as G-CSF and GM-CSF, activate downstream signaling pathways, particularly STAT3 and STAT5, which drive the expression of lipid transport receptors such as CD36 on MDSCs." (PMID 40361394, 2025). "In this context, the significantly increased MFE (%) of the CD36High HCC1954 cell subset supports the hypothesis that CD36 is expressed mainly in the stem cell component compared with the tumor bulk counterpart (No CSCs) of this cell line." (PMID 39833955, 2025). "Furthermore, the results of IHC staining of tumor sections showed that the expression of Ki-67 and vimentin in CD36−/− mice was much lower than that in C57BL/6J mice, while BAX expression was higher in CD36−/− mice." (PMID 38319449, 2024). "Nevertheless, the role of tumor-derived EVs in inducing CD36 expression in the recipient cells is not understood, which may directly impact the deregulation of lipid metabolism." (PMID 39062552, 2024). "Collectively, the elevated expression of CD36 and ANGPTL4 in overweight/obese TNBC patients may suggest more extensive metabolic reprogramming of cancer cells in response to the obese adipose tissue tumor microenvironment." (PMID 39456610, 2024). "Notably, AKR1B1, CD36, ABCA1, PRKD1, OSBPL1A, and FABP3 showed varied expressions in specific cells, suggesting their significant roles in STAD carcinogenesis, further confirmed by elevated mRNA levels in tumor tissues via qRT-PCR." (PMID 38440405, 2024). "Consistent with the increased secretion of FFAs from beige adipocytes in the tumor microenvironment (TME), cells incubated with adipocyte CM pretreated with MIIP+/− cancer cell CM exhibited higher expression levels of FFA transporters, CD36 and FABP4, compared to cells treated with WT (MIIP+/+) CM." (PMID 38245780, 2024). "Thus, increased lipase activity within the tumor and elevated CD36 expression favors lipid mobilization and utilization in the tumor-EC compartment when endothelial Angptl4 is absent." (PMID 38086791, 2023). "We first knocked out Cd36, Tlr2, or Tlr6 in DCs by CRISPR‐Cas9 technique and found that the ASC speck formation was significantly reduced in the Cd36CRISPR‐/−, Tlr2CRISPR‐/− or Tlr6CRISPR‐/− DCs in comparison with that in wild‐type DCs after co‐culture with the Arf1‐ablated tumor cells." (PMID 37786300, 2023). "Vascular CD36 expression was consistently absent within the tumor area relative to vascular CD31 expression in specimens from multiple IBC subtypes (ER+PR+/−HER2− [n = 18], ER+PR+/− HER2+ [n = 3], ER−PR−HER2+ [n = 4], ER−PR−HER2− [n = 7], and unknown [n = 8])." (PMID 37816052, 2023). "And the mechanism of CD36+CD8+ T cells leading to tumor progression was not clear." (PMID 37085798, 2023).
tumor (continued). "Our scRNA-seq data and TCGA data showed a positive correlation between CD36+ CAFs and MDSCs, but an inverse correlation was observed for effector T cells (GZMB+CD8+), which was validated by IF assays in paraffin-embedded tumor sections from 30 primary HBV-related cases." (PMID 36878933, 2023). "Furthermore, in mice subjected to genetic ablation, the combination of CD36−/− CD8+T cells and anti-PD-1 antibody achieved better anti-tumor effect and prolonged mouse survival than the combination of WT CD8+T cells and anti-PD-1 antibody or CD36−/− CD8+T cells." (PMID 36354702, 2022). "Notably, the internalization of tumor-derived lipids by macrophages was markedly decreased when CD36 was absent in vitro." (PMID 36184646, 2022). "In addition, CD36-dependent lymph node metastases increased in size and frequency upon being treated with PA, without affecting the primary tumour growth." (PMID 36428985, 2022). "Whilst it is likely that alteration of CD1d expression will in turn enable tumour escape from NKT cell-mediated immunosurveillance, it is also possible that altered expression of CD1d contributes to metabolic alterations in tumour cells by regulating CD36 functions." (PMID 36344546, 2022). "Inhibition of STAT3 or STAT5 signaling or genetic depletion of the fatty acid translocase CD36 inhibits the activation of oxidative metabolism and the induction of immunosuppressive function in tumor-infiltrating MDSC and results in a CD8+ T-cell-dependent delay in tumor growth." (PMID 35408873, 2022). "Fatty acid taken via CD36 is mostly stored rather than used for fatty acid oxidation, which may promote ferroptosis in CD36-overexpressing tumor cells." (PMID 35978815, 2022). "Although CD36 inactivation in killer T cells could bolster theanti-tumor effect, it is not clear how its systemic targeting in other cell types mightaffect disease progression long-term." (PMID 34603769, 2021). "Weak or no CD36 expression was present 19 (10.6) of tumour tissues with adipocyte infiltration." (PMID 34561446, 2021). "CD36 not only promotes tumor metastasis and treatment resistance by promoting lipid uptake and FA oxidation, but also inhibits angiogenesis by binding with TSP-1, thus inducing tumor microvascular endothelial cell apoptosis or blocking the vascular endothelial growth factor receptor 2 pathway 5-7." (PMID 34234847, 2021). "As far as the current literature goes, normal keratinocytes do not require CD36 for their metabolism; it is only transiently expressed in pathological circumstances such as wounds, infectious and autoimmune cutaneous diseases and tumor-related pathologies." (PMID 33917064, 2021). "CD36 expression varied in tumour tissues, with 33 (18.3%) having weak or no CD36 expression." (PMID 34561446, 2021). "CD8+ TILs uptake fatty acids mediated by increased CD36, which is induced by cholesterol in TME and participates in lipid peroxidation and ferroptosis, leading to decreased cytotoxic cytokine production and impaired anti-tumor ability in an oxidized lipid-CD36-p38 kinase manner." (PMID 34858835, 2021). "However, CD36 knockdown using CD36 shRNA #4 in HT29 LuM3 cells, which have higher levels of CD36 expression as well as higher metastatic potential, lead to a more prominent inhibition of tumor growth and a decrease in tumor weight." (PMID 32850342, 2020). "However, both CD36 and LAMA3 are involved in ECM-receptor interaction pathways and if their functions were somehow disrupted, this could provide a mechanism for tumor spread." (PMID 32954225, 2020). "In contrast to HCT116 cells, CD36 knockdown in HT29 did not significantly affect tumor growth, suggesting that this cell line may not be dependent on CD36 due to considerably lower CD36 expression as compared to HCT116 cells." (PMID 32850342, 2020).
tumor (continued). "First, phagocytosis of extracellular fatty acids via surface receptors including CD36, Olr1 (LOX1), and CD204 is a steady way in a fatty acid‐enriched environment, for instance, in a tumor microenvironment, explaining, that CD204 is suggested to be a marker of tumor‐infiltrated macrophages." (PMID 31602788, 2019). "Silencing of the PPAR-α and CD36 genes significantly attenuated the FFA induced EpCAM, β-catenin and cyclinD1, further confirmed that FFA and FGF15/FGFR4 signaling could play a critical role in contributing to tumor-initiation and the development of HCC." (PMID 29973237, 2018). "Conversely, inhibition of STAT3 or STAT5 signaling or genetic deletion of the fatty acid translocase CD36 inhibits the activation of oxidative metabolism and prevents the immunosuppressive function of MDSC leading to enhanced CD8+ T cell functionality and delay in tumor growth." (PMID 30123774, 2018). "However, there is an ~54%, but not statistically significant, reduction in tumor infiltrating macrophages (F4/80) that were of the M2 phenotype (F4/80+iNOS-CD206+CD36+)." (PMID 30034628, 2018). "Moreover, activated γδ T cells are able to phagocytose tumor antigens and apoptotic or live cancer cells possibly through the scavenger receptor CD36 in a C/EBPα (CCAAT/enhancer-binding protein α)-dependent mechanism and mount a tumor antigen-specific CD8+ T-cell response." (PMID 28713381, 2017). "Furthermore, multiple receptors interacting with different S100 proteins or S100A8/A9 heterodimers are expressed by both tumor cells and TAMs (SCARA/B, CD36), preferentially by TAMs (AGER, MSR1, TLR4) or by tumor cells (ERBB2), pointing to extensive functional interactions between both cell types." (PMID 27215396, 2016). "Through its original mechanism of action which supposes concomitant disruption of TSP-1:CD47 interaction and enhancement of CD36 activation by TSP-1, TAX2 may inhibit tumor progression while limiting many of the undesired side effects of broadly inhibiting important physiological functions of CD47." (PMID 26578962, 2015). "Integrated genomic analysis of microarray data from primary tumours of the two different isogenic pairs revealed that MMP-3, Pthlh and S100a8 were commonly upregulated and that Cd36 was commonly downregulated, indicating that these genes might be causal in tumour cell dissemination." (PMID 25633981, 2015). "CD36 also demonstrated positive correlations with immune checkpoint molecules, including C10orf54, EDNRB, TLR4, ENTPD1, IL10, and IL2RA, suggesting that it may contribute to immune escape mechanisms by engaging checkpoint pathways in the tumor microenvironment." (PMID 41550652, 2025). "Moreover, CD36 levels were notably higher in neutrophils from metastatic OSCC tumors compared to non-metastatic tumors (p = 0.0049), suggesting that CD36 might contribute to the unique metabolic demands or immune evasion strategies of metastatic tumor sites." (PMID 40549016, 2025). "CD36 also exhibited positive correlations with several immunostimulators, including C10orf54, CXCL12, ENTPD1, CD28, and TNFSF18, suggesting that it may contribute to immune activation pathways and modulation of antitumor immune responses in the tumor microenvironment." (PMID 41550652, 2025). "However, the supposed basic mechanism of an adipocyte-driven tumour progression in SARIFA-positive cancers may provide the basis for pharmacological intervention targeting the tumour cell metabolism with existing drugs such as Metformin, FABP4-inhibitors or CD36." (PMID 38123705, 2024). "Thus, in addition to perturbing tumor growth, metastasis, and drug resistance via targeting CD36 in cancer cells, the concurrent inhibition of CD36 on intratumoral Tregs, CD8+ T cells, and M2 TAMs would offer the additional bonus of eliciting anti-tumor immunity to further reduce the tumor burden." (PMID 37371076, 2023).
tumor (continued). "Furthermore, when stimulated by tumor antigens, γδ T cells will up-regulate the expression of antigen-presenting molecules HLA-DR, costimulatory and adhesion molecules (CD80, CD86, CD40) and scavenger receptor CD36, which allow γδ T cells to participate in the elimination of tumor cells." (PMID 32413966, 2020). "In vitro studies indicated that hypoxia increased lipid accumulation in tumor cells, and this phenomenon depended at least in part from increased uptake of exogenous lipids and was associated with increased AMPK activation and expression of the lipid importer CD36 (data not shown)." (PMID 31835444, 2019). "In addition to affecting proliferation of CSCs, uptake of palmitic acid via CD36 also specifically activates the metastatic potential of CD44bright oral squamous cell carcinoma (OSCC) metastasis-initiating cells, highlighting the central role of lipids uptake in fueling tumor metastasis." (PMID 29907133, 2018). "Indeed, TSP-1/CD36/CD47 trimolecular signaling platform dynamics as well as interactions involving co-receptors and soluble ligands exert pleiotropic activities on cancer progression, by directly modulating cancer cells behavior or by acting on tumor microenvironment stromal cells." (PMID 26578962, 2015). "Additionally, the expression levels of TGFB and PORCN also showed positive correlation with CD36 expression, suggesting that the TGF-β and Wnt/β-catenin signaling pathways may be the drivers of EMT program activation in the tumor samples with elevated CD36 levels." (PMID 26424075, 2015). "However, Cd36 levels were not significantly downregulated in the more metastatic tumour cells." (PMID 25633981, 2015). "Results showed that some of the most relevant pathway’s regulators and effectors (CD36, FABP4, PLIN1, PLIN4, SCD5 and ACSL6) showed significantly lower expression in tumor tissue samples (p.adjusted < 0.01, data not shown)." (PMID 40860798, 2025). "Bmp5+ lobular-like fibroblasts and Cd36+ committed preadipocytes were not present within tumors, while Acta2 (α-SMA)+ myCAFs presented new tumor clusters not found in hyperplastic glands (Fig. EV5H,I)." (PMID 40216939, 2025). "Furthermore, antitumor immunomodulatory effects in tumor-bearing hosts have been demonstrated; a decrease in Tregs and MDSCs and an increase in CD8+ T cell-producing IFN-γ and granzyme B was shown, suggesting that the combination of ICIs and CD36 inhibitors may have synergistic effects." (PMID 39273384, 2024). "Therefore, it is reasonable to speculate that tumour‐infiltrating CD8+ T cells become dysfunctional in the high‐lipid, low‐glucose, hypoxic microenvironment, a process that may be related to CD8+ T lymphocyte‐mediated lipid uptake via CD36, leading to lymphocyte dysfunction." (PMID 37184113, 2023). "For the fatty acid transporters, there was no variation in the expression of CD36 between groups, albeit lower in PY8119 tumors, while CPT1a expression was significantly increased in tumors from HFD-fed mice for both tumor models." (PMID 35158830, 2022). "Conversely, M2 macrophages express an abundant level of non-opsonic receptors (e.g., CD163, CD36, CD206), produce anti-inflammatory cytokines and contribute in many ways to tumor progression." (PMID 33924378, 2021). "Statistical analysis of correlation between FASN and CD36 revealed a significant negative correlation between FASN and CD36 mRNA levels in tumor tissues, but not in normal tissues." (PMID 32850342, 2020). "Results showed SW480 LV-CD36 cells suppressed tumor growth by 63%, while knockdown of CD36 in RKO cells increased tumor growth by 76%, when compared to their negative controls, respectively." (PMID 31484922, 2019). "Alternatively, CD36-neutralizing antibodies block extracellular lipid uptake of CSCs in OSCC and markedly inhibits tumor growth without side effects." (PMID 29907133, 2018).
tumor (continued). "Given the role of CD36 in enhancing ferroptosis through the transcriptional upregulation of CAV1 in TNBC, we further investigated the potential of ferroptosis activators to effectively inhibit TNBC tumor metastasis in the absence of CD36." (PMID 41267927, 2025). "However, through dual-color immunofluorescence, we found that CD36 was highly expressed on T cells rather than tumor cells in NSCLC, and CD36 blockage will exert little effect on the ferroptosis in tumor cells theoretically." (PMID 37085798, 2023). "Furthermore, in a preclinical model of liver metastasis, the absence of CD36 in macrophages restores liver CD8+T cell immunity and suppresses metastatic tumor growth." (PMID 36184646, 2022). "However, expression levels of FABP1, CD36, IRS1, THBS1, and TGFB1 did not significantly differ in various tumor stages." (PMID 36193307, 2022). "Thrombospondin-1 (TSP-1), a potent inhibitor of angiogenesis that predominantly acts through its receptor CD36, has been reported to inhibit inflammatory lymphangiogenesis, whereas TSP-1 did not inhibit tumor-induced lymphangiogenesis in a chemical skin carcinogenesis model." (PMID 33731707, 2021). "Moreover, although the opsonization of tumor cells with murlentamab did not modify the proportion of TAMs expressing CD163, it decreased the proportion of TAMs positive for CD36 and CD206." (PMID 33924378, 2021). "Indeed, we found that inhibition of FASN selectively upregulates CD36 mRNA and protein expression, but not expression of other FA transporters in multiple models including CRC cells, tumor xenografts, genetically modified mice and in human tissues." (PMID 32850342, 2020). "Interestingly, statistical analysis via Spearman Correlation showed a positive correlation between expression of CD36 and FASN in primary CRC tumor tissues, but it was not statistically significant (Spearman r = 0.21743, n = 56)." (PMID 32850342, 2020). "However, unlike that of CD36 and FATP4, the staining intensity of ACSL1 was remarkably reduced in tumor tissues compared to normal cells." (PMID 31089396, 2019). "Because CD47 and CD36 can competitively bind to TSP-1, CD36 might endow tumor-radiotherapy resistance to normal tissues and protect nontumor tissues against radiation damage and enhance the efficacy of radiotherapy." (PMID 31410189, 2019). "We observed that both the CD36 and OGT levels could patients with a higher pStage (stages III and IV), deeper tumor invasion (T3 and T4) and more positive lymph nodes (>5), while the combination of the CD36 and OGT levels showed a high overall accuracy." (PMID 31410220, 2019). "In the case of CD36, constitutive activation, regardless of TSP expression within the tumour or tumour niche, could be largely overlooked if the main focus falls on the ligand rather than the receptor." (PMID 30069479, 2018). "As such, we hypothesized that tumors formed in mice lacking HRG will display increased CD36-TSP signaling resulting in decreased in vascularization and tumor growth." (PMID 22808089, 2012).